RANBP9 (RAN binding protein 9)
Description:
May act as scaffolding protein, and as adapter protein to couple membrane receptors to intracellular signaling pathways (Probable). Acts as a mediator of cell spreading and actin cytoskeleton rearrangement. Core component of the CTLH E3 ubiquitin-protein ligase complex that selectively accepts ubiquitin from UBE2H and mediates ubiquitination and subsequent proteasomal degradation of the transcription factor HBP1. May be involved in signaling of ITGB2/LFA-1 and other integrins. Enhances HGF-MET signaling by recruiting Sos and activating the Ras pathway. Enhances dihydrotestosterone-induced transactivation activity of AR, as well as dexamethasone-induced transactivation activity of NR3C1, but not affect estrogen-induced transactivation. Stabilizes TP73 isoform Alpha, probably by inhibiting its ubiquitination, and increases its proapoptotic activity. Inhibits the kinase activity of DYRK1A and DYRK1B. Inhibits FMR1 binding to RNA.
Synonyms: RanBPM; BPM-L; BPM90; RanBP7
Tractability: Antibody: UniProt places it where antibodies can reach, with high confidence; its Gene Ontology location is reachable by antibodies, with medium confidence. PROTAC: UniProt records ubiquitination sites on it; ubiquitination databases record sites on it; its protein half-life has been measured.
Gene: Protein-coding gene on chromosome 6 (13,621,498 to 13,712,087, reverse strand). Ensembl gene ENSG00000010017.
Subcellular location: Cytoplasm; Nucleus; Cell membrane
Subcellular location (Human Protein Atlas): Nucleoplasm; Cytosol; Nuclear bodies
Pathways (Reactome):
Signal Transduction: MET activates RAS signaling; RAF/MAP kinase cascade
Developmental Biology: L1CAM interactions
Metabolism: Regulation of pyruvate metabolism
Gene Ontology:
Molecular function: enzyme binding; protein binding; protein-macromolecule adaptor activity; small GTPase binding
Biological process: negative regulation of ERK1 and ERK2 cascade; cytoskeleton organization; microtubule nucleation; positive regulation of amyloid precursor protein catabolic process; proteasome-mediated ubiquitin-dependent protein catabolic process; protein-containing complex assembly
Cellular component: cytoplasm; cytosol; nuclear body; nucleoplasm; nucleus; plasma membrane; ubiquitin ligase complex; GID complex; microtubule associated complex
Genetic constraint (gnomAD): Loss-of-function variants: 11 observed, 57.04 expected, observed/expected ratio (o/e) 0.19, 90% interval 0.12 to 0.32. The synonymous counts are far from expectation, so gnomAD's model fits this gene poorly and the ratio says little. Missense variants: 683 observed, 726.58 expected, observed/expected ratio (o/e) 0.94, 90% interval 0.88 to 1. Synonymous variants: 331 observed, 273.7 expected, observed/expected ratio (o/e) 1.21, 90% interval 1.11 to 1.33.
Homologues: Orthologues: chimpanzee RANBP9 (99% identical), macaque RANBP9 (99% identical), pig RANBP9 (98% identical), mouse Ranbp9 (93% identical), rat Ranbp9 (93% identical), dog RANBP9 (93% identical), guinea pig RANBP9 (75% identical), rabbit RANBP9 (74% identical), zebrafish ranbp9 (68% identical), tropical clawed frog ranbp9 (57% identical), Drosophila melanogaster RanBPM (44% identical). Paralogues in human: RANBP10 (58% identical), SPRYD3 (14% identical), GID8 (9% identical).
Diseases named in the same sentence as RANBP9 in open-access papers:
RANBP9 is named in the same sentence as 37 diseases in open-access papers, as found by Europe PMC text mining. Sharing a sentence is not in itself a finding about the gene and the disease. The quoted sentences say what the papers report.
Alzheimer disease (8 papers, 2013 to 2023). A progressive, neurodegenerative disease characterized by loss of function and death of nerve cells in several areas of the brain leading to loss of cognitive function such as memory and language. "RANBP9 interacts with proteins involved in Alzheimer’s disease and has been associated with schizophrenia." (PMID 36959830, 2023). "The overexpression of RanBP9 is associated with diminished learning and memory in Alzheimer’s disease mouse models." (PMID 36079709, 2022). "We recently demonstrated that RanBP9 plays pathogenic role in Alzheimer’s disease." (PMID 23840553, 2013). "It has been shown to directly regulate the amyloid-β precursor protein (APP) and Ran-binding protein 9 (RanBP9) as well as MAPK1, which are all implicated in the pathology of Alzheimer’s disease." (PMID 37584866, 2023). "Among the top hub genes associated with the common factor, TOB1, RANBP9, HSPB3, and SRSF3 were also linked to neurodegenerative disorders, such as Alzheimer’s disease, Parkinson’s, and amyotrophic lateral sclerosis, through various pathways." (PMID 36959830, 2023). "Comprehensive reviews about proposed biological roles of RANBP9 in cancer, Alzheimer’s disease and other contexts are available." (PMID 29914204, 2018).
non-small cell lung carcinoma (6 papers, 2019 to 2025). A group of at least three distinct histological types of lung cancer, including non-small cell squamous cell carcinoma, adenocarcinoma, and large cell carcinoma. "This specific interest was prompted by the earlier observation that RanBP9 is highly expressed in lung alveolar macrophages, both in human and mouse, both in normal conditions and in tumor associated macrophages of non-small cell lung cancer masses." (PMID 40223093, 2025). "Due to the weakening of DNA repair in RanBP9-deficient cells, RanBP9 has been put forward as a potential target of therapy in non-small cell lung cancer." (PMID 40223093, 2025). "In particular, we provide the first RanBP9-associated interactome enriched from lung macrophages motivated by the earlier observation that normal alveolar macrophages and tumor associated macrophages in non-small cell lung cancer express high levels of this protein." (PMID 40223093, 2025). "In a retrospective clinical study, we have recently shown that the levels of RANBP9 protein are inversely correlated with non-small cell lung cancer patient survival in a cohort of patients treated with platinum-based drugs." (PMID 31885576, 2019).
lung carcinoma (5 papers, 2016 to 2025). "Our group has found that the ablation of RANBP9 in lung cancer cells renders them more sensitive to ionizing radiation and cisplatin exposure." (PMID 29914204, 2018). "All together, our results showed that RanBP9 is critically involved in the early steps of DDR in lung cancer cells, acting both as target and co-regulator of ATM in the effective activation of the DNA repair machinery." (PMID 26943034, 2016). "Our data show that knockdown of RanBP9 negatively affected the ability of lung cancer cells to repair damaged DNA by HR." (PMID 26943034, 2016). "In response to IR, RanBP9 rapidly accumulates into the nucleus of lung cancer cells, but this nuclear accumulation is prevented by ATM inhibition." (PMID 26943034, 2016). "In the present study, we investigated the role of RanBP9 in the response and sensitivity to DNA damage of lung cancer cells exposed to IR." (PMID 26943034, 2016). "Here, we show a significant interaction between active ATM and RanBP9 in lung cancer cells at early time points following IR exposure." (PMID 26943034, 2016). "Human lung cancer proteins showing positive correlation with RANBP9, for both LUAD and LUSQ cohorts, demonstrated significant positive enrichment scores for RANBP9 associated proteins in A549, candidates with differential ubiquitylation, and literature-defined CTLH associated gene lists." (PMID 40883813, 2025). "For instance, RANBP9 is a mediator of cellular DNA damage response in lung cancer cells." (PMID 37924135, 2023). "To explore this hypothesis, we generated stable clones of lung cancer cell lines of different origins in which RanBP9 expression was stably silenced." (PMID 26943034, 2016). "The observation that RanBP9 abrogation enhances the sensitivity to genotoxic treatments (IR and cisplatin) of specific lung cancer cells invites to speculate that compounds inhibiting RanBP9 activity in DDR might represent a new strategy to induce synthetic lethality." (PMID 26943034, 2016). "Finally, we tested whether RanBP9 expression affects the sensitivity to other genotoxic treatments, currently used in the clinic for lung cancer therapy, such as cisplatin." (PMID 26943034, 2016). "Then, we performed co-immunoprecipitation experiments using total cell extracts from lung cancer cell lines of different origin (A549, H460, and H1299), expressing detectable amounts of both ATM and RanBP9 proteins, plus or minus exposure to IR to activate the ATM kinase." (PMID 26943034, 2016). "To evaluate the potential role of RanBP9 in the regulation of ATM-dependent activation of the DDR, we generated stable clones from three lung cancer cell lines expressing a negative control shRNA or a RanBP9-silencing shRNA." (PMID 26943034, 2016).
breast carcinoma (4 papers, 2016 to 2020). "Amplifications of RANBP9 occur in breast cancer in vivo and are associated with increased gene expression, although amplifications are less common than for ERBB2, suggesting other mechanisms more typically driving its overexpression." (PMID 30205839, 2018). "Thus, the cancer cell eQTL analysis suggests that RANBP9 may be an important driver of breast cancer risk and progression, and the possible oncogenic effects of this gene could represent an interesting starting point for functional studies." (PMID 30205839, 2018). "rs204247 tags the promoter of RANBP9 as well as upstream putative enhancers (in MCF7 breast cancer cells)." (PMID 30205839, 2018). "The interaction model indicates that the risk allele (G; per-allele odds ratio = 1.06 (95% CI = 1.03–1.1)) increases the expression of RANBP9 in breast cancer cells." (PMID 30205839, 2018). "Consistent with an oncogenic effect, RANBP9 is overexpressed in a similar proportion of breast cancer patients as ERBB2—an important driver of breast cancer (13.04% and 14.13% respectively)." (PMID 30205839, 2018). "RANBP9 is ubiquitously and highly expressed in human tissues and breast cancer cell lines, but this eQTL is only evident in esophagus mucosa (P = 2 × 10− 8) and aorta (P = 3.9 × 10− 5) in GTEx." (PMID 30205839, 2018). "If rs204247 affects RANBP9 expression only in breast cancer cells, and this is indeed the mechanism by which this SNP predisposes individuals to cancer, then some earlier aberration, for example, the activation of a transcription factor, must be a prerequisite for rs204247’s pathogenic effect." (PMID 30205839, 2018). "However, there is an exception for the SNP rs204247, which affected the expression of RANBP9 in breast cancer cells only." (PMID 30205839, 2018). "Furthermore, we also showed that one breast cancer risk variant, rs204247, is an eQTL for RANBP9 in breast cancer cells, but not tumor-associated normal cells." (PMID 30205839, 2018).
renal carcinoma (4 papers, 2010 to 2016). A carcinoma arising from the epithelium of the renal parenchyma or the renal pelvis. "The support for this notion comes from the observation that overexpression of RanBP9 in human renal carcinoma cell line; A704 increased the cell migration." (PMID 23840553, 2013).
Azoospermia (3 papers, 2014 to 2021). Absence of any measurable level of sperm,whereby spermatozoa cannot be observed even after centrifugation of the semen pellet. "Nevertheless, Ranbp9-null spermatocytes and spermatids appeared to be constantly depleted, leading to a complete lack of spermatozoa in the epididymis, resembling azoospermia in humans." (PMID 25474150, 2014).
gastric cancer (3 papers, 2017 to 2019). A primary or metastatic malignant neoplasm involving the stomach. "For example, reduced expression of RANBP9 associated with distant metastasis and chemoresistance in gastric cancer." (PMID 31885576, 2019). "Knockdown of RANBP9 was also reported to sensitize gastric cancer cells to methotrexate." (PMID 31885576, 2019).
osteosarcoma (3 papers, 2016 to 2020). A usually aggressive malignant bone-forming mesenchymal neoplasm, predominantly affecting adolescents and young adults. "Ezrin is the only other protein associated with metastasis in osteosarcoma, and this relationship was confirmed in this study (P<0.001), with negative correlations observed between the expression of Ezrin and RanBP9 or TSSC3 (P<0.001)." (PMID 28032865, 2016). "Taken together, we inferred that loss of RanBP9/TSSC3 expression may be associated with lung metastasis in human osteosarcoma." (PMID 28032865, 2016). "Our study demonstrates that a ternary RanBP9/TSSC3/Src complex forms in osteosarcoma cells and can be significantly augmented or inhibited by overexpressing or knocking down RanBP9." (PMID 28032865, 2016). "These in vivo results corroborate our in vitro findings to highlight a significant functional role for the RanBP9/TSSC3 complex in the regulation of lung metastasis in osteosarcoma." (PMID 28032865, 2016). "Indeed, exposure of RanBP9-overexpressing osteosarcoma cells to pYEEI restored Src kinase activity and suppressed anoikis." (PMID 28032865, 2016). "To confirm whether the RanBP9/TSSC3 complex suppresses metastasis in osteosarcoma, we established an in vivo lung metastasis model by injecting transfected MTF cells into the tail vein of nude mice." (PMID 28032865, 2016). "Gain-and-loss or loss-and-gain functional approaches confirmed that RanBP9 and TSSC3 functioned cooperatively, likely as a protein complex, to modify anoikis resistance, anchorage-independent growth, and more importantly, the metastatic ability of osteosarcoma cells." (PMID 28032865, 2016). "The involvement of RanBP9 in regulating the PHLDA2 expression has been described previously; however, the transcriptional mechanism by which PHLDA2 is repressed in osteosarcoma has been elusive." (PMID 31058093, 2019). "We characterized a novel interaction between RanBP9 SPRY domain and TSSC3 PH domain by which RanBP9/TSSC3 complex exerts transcription and post-translation regulation in osteosarcoma." (PMID 28032865, 2016). "Co-immunoprecipitation of SaOS2, MTF and MG63 cell lysates, where both endogenous RanBP9 and TSSC3 protein are expressed, confirmed the formation of a complex between RanBP9 and TSSC3 in osteosarcoma cells." (PMID 28032865, 2016). "Taken together, we conclude that the functional interaction between RanBP9 and TSSC3 regulates anoikis resistance in osteosarcoma." (PMID 28032865, 2016). "This study provides a biological basis for exploring the therapeutic significance of dual targeting of RanBP9 and TSSC3 in osteosarcoma." (PMID 28032865, 2016). "Mechanistically, we characterized the novel functional interaction among RanBP9 and TSSC3 as well as Src, and demonstrated that this complex cooperated to regulate anoikis resistance, migration, invasion and metastasis in osteosarcoma." (PMID 28032865, 2016). "RanBP9/TSSC3 complex was inversely correlated with a highly anoikis-resistant phenotype in osteosarcoma cells and metastasis in human osteosarcoma." (PMID 28032865, 2016). "The functional interaction between RanBP9 and TSSC3 directly regulates anoikis resistance and metastasis, and provides a biological basis for further exploration of the therapeutic significance of dual targeting RanBP9 and TSSC3 in osteosarcoma." (PMID 28032865, 2016). "Our study definitely indicates that both RanBP9 and TSSC3 have an essential tumor-suppressor role to prevent metastasis and may represent useful clinical predictors of metastases and/or prognostic factors in osteosarcoma." (PMID 28032865, 2016). "The positive rates of RanBP9 and TSSC3 were 23% (3/13) and 38% (5/13), respectively, in osteosarcoma with metastasis, as well as 91% (61/67) and 88% (59/67), respectively, in osteosarcoma without metastasis." (PMID 28032865, 2016).
infertile (2 papers, 2014 to 2015). "In contrast, the progressive spermatogenic disruptions and male subfertility or infertility in adult gcKO mice demonstrate the importance of Ranbp9 in male germ cell development." (PMID 25474150, 2014). "Moreover, we observed down-regulation of RANBP9 transcript in the asthenozoospermic group in comparison to the normozoospermic infertile group." (PMID 25973848, 2015). "These Ranbp9-null male mice, even if they survived, were completely infertile." (PMID 25474150, 2014).
neuroblastoma (2 papers, 2013 to 2014). Neuroblastoma (NB) is the most common solid, extracranial childhood tumor. "To determine whether the RanBP9 gene is a target of miR-101, we introduced a firefly reporter vector containing the full-length RanBP9 3′UTR (883 bp) downstream of the luciferase open reading frame into SH-SY5Y neuroblastoma cells." (PMID 24592211, 2014).
viral infections (2 papers, 2020 to 2025). "Interestingly, RanBP9-3xHA pulled down Parp12 (Poly[ADP-ribose] polymerase member 12), which had been previously reported as RanBP9 interactor, and is an interferon stimulated gene that contributes to suppressing viral infections." (PMID 40223093, 2025).
glioblastoma (1 paper, 2025). The most malignant astrocytic tumor (WHO grade IV). "However, since RANBP10 has been reported to promote glioblastoma cell growth and RANBP9 silencing can increase proliferation, we can speculate that these effects are likely cell type dependent." (PMID 40883813, 2025). "In contrast, the downregulation of RANBP9 in HEK293 cells increased cell proliferation, and the silencing of RANBP10 was found to reduce glioblastoma cell proliferation." (PMID 40883813, 2025).
Huntington disease (1 paper, 2025). Huntington disease (HD) is a rare neurodegenerative disorder of the central nervous system characterized by unwanted choreatic movements, behavioral and psychiatric disturbances and dementia. "Interestingly though, there were also terms that suggest the involvement of RanBP9 and the CTLH complex in “Huntington disease”, “translation”, “glyceraldehyde-3-phosphate biosynthetic process”, “adaptive innate immunity”, and “positive regulation of phagocytosis”." (PMID 40223093, 2025).
male infertility (1 paper, 2015). The inability of the male to effect fertilization of an ovum after a specified period of unprotected intercourse. "We observed differential expression of a number of transcripts, such as PRM1, SPATA18, TNP1, EIF4G2, CANX, RANBP9, TCP11, which have previously been associated with male infertility." (PMID 25973848, 2015).
prostate carcinoma (1 paper, 2021). A carcinoma that arises from epithelial cells of the prostate gland. "In AR-positive prostate cancer cells, RANBP10 formed a protein complex with itself or RANBP9 and then elevated the transcription activity of AR." (PMID 34671019, 2021).
sterility (1 paper, 2025). "While the absence of RanBP9 causes perinatal lethality, occasional RanBP9-deficient mouse survivors on a mixed genetic background display reduced body size and severe sterility both in males and females." (PMID 40223093, 2025).
tauopathies (1 paper, 2025). "This suggests that the RANBP9-tau interaction may also be more prevalent in AD than in tauopathies." (PMID 40317322, 2025).